HHIP (hedgehog interacting protein)
Diseases named in the same sentence as HHIP in open-access papers (continued):
Sharing a sentence is not in itself a finding about the gene and the disease.
pancreatic cancer (10 papers, 2013 to 2025). "HHIP is located on chromosome 4q31.21~31.3 that has been confirmed to be a target for allele loss in malignant tumors such as pancreatic cancer and liver cancer." (PMID 31765425, 2019). "In a separate genome-wide association study, common variants in the SHH, BTRC and HHIP genes have been associated with the risk of pancreatic cancer." (PMID 23826113, 2013). "The genomic region surrounding HHIP (hedgehog-interacting protein) has been implicated in many cancers, with hypermethylation of the promoter region found to down-regulate the expression of HHIP found in many tumors, such as gastric and pancreatic cancer." (PMID 24774302, 2014). "For example, the hypermethylation of hedgehog-interacting protein (HHIP), a gene encodes for a negative regulator of Hh signaling, was determined in pancreatic cancer samples." (PMID 36084949, 2022). "This suggests that methylation of the HHIP promoter contributes to the upregulated Hedgehog signaling in pancreatic neoplasms." (PMID 30423843, 2018). "Down regulation of HHIP in pancreatic cancer has been shown to be mediated through epigenetic CpG hypermethylation within the promoter region." (PMID 23671415, 2013). "HHIP inhibits Shh signaling by sequestering Hh ligands which then cannot activate the pathway, and its epigenetically mediated downregulation was observed in gastrointestinal, hepatocellular, and pancreatic tumors." (PMID 27553089, 2017). "Hedgehog-interacting protein (HHIP), a negative regulator of Hh signaling which is normally downregulated or absent in pancreatic cancer, was considered to be the target of genetic and epigenetic modifications." (PMID 30423843, 2018). "The HHIP promoter underwent partial and complete methylation in several pancreatic cancer cell lines, primary pancreatic cancers, and pancreatic cancer xenografts, whereas no methylation was found in normal pancreata." (PMID 30423843, 2018).
emphysema (9 papers, 2015 to 2025). "Together, these data suggest that Hhip deficiency is sufficient to drive emphysematous changes, and HHIP-Fc can attenuate BPD-associated emphysema." (PMID 40333979, 2025). "Genome-wide association studies (GWAS) in several human cohorts have consistently identified susceptibility locus for COPD/emphysema on chromosome 4q31 adjacent to hedgehog-interacting protein (HHIP) gene." (PMID 31323955, 2019). "In summary, HHIP haploinsufficiency exaggerated CS-induced airspace enlargement, which models CS-induced emphysema in human smokers carrying COPD risk alleles at the HHIP locus." (PMID 25763110, 2015). "In addition, our data show that administering HHIP-Fc protein during the alveolar development stage significantly alleviates BPD-associated emphysema." (PMID 40333979, 2025). "To determine whether BPD-associated emphysema can be prevented by correcting neonatal alveolar development, we administered HHIP-Fc protein to HhipLacZ/+ mice at the neonatal stage and analyzed lung morphology at 8 weeks of age." (PMID 40333979, 2025). "BPD is a major risk factor for COPD/emphysema, with HHIP implicated in both conditions." (PMID 40333979, 2025). "Previously reported associations of these genetic variants include: airflow limitation (CHRNA3/5, IREB2, HHIP), emphysema susceptibility and severity (CHRNA3/5, BICD1), chronic bronchitis phenotype, exacerbation rate (HHIP) and pulmonary hypertension pathogenesis." (PMID 35330379, 2022). "However, there is still a lack of studies that examine the association between hedgehog activation and HHIP-related emphysema." (PMID 31323955, 2019). "Therefore, we hypothesized that HHIP deficiency in neonates leads to alveolar malformation, which subsequently causes emphysema in adults." (PMID 40333979, 2025). "Our previous study demonstrated a protective role of HHIP against COPD/emphysema acute exacerbation." (PMID 40333979, 2025). "Our findings demonstrate that HHIP drives myofibroblast transition, inhibits epithelial stem/progenitor cell senescence, and guards against BPD and BPD-associated emphysema via suppressing Hh-IGF1 signaling axis." (PMID 40333979, 2025). "We identify hedgehog-interacting protein (HHIP), associated with both BPD and emphysema, as a critical regulator of alveologenesis." (PMID 40333979, 2025). "Although HHIP locus has been consistently associated with the susceptibility to COPD including airway remodeling and emphysema in genome-wide association studies, the molecular mechanism underlying this genetic association remains incompletely understood." (PMID 33907231, 2021). "Although there are possible explanations for the role of the HHIP protein in emphysema physiopathology in murine models, the mechanism concerning COPD in humans remains to be elucidated." (PMID 33193570, 2020). "Our study demonstrates how HHIP, through restricting Hh activation, can modulate the dynamic changes of myofibroblasts and protect alveologenesis, providing a theoretical rationale for the clinical trial of HHIP-Fc recombinant protein for BPD and BPD-associated emphysema." (PMID 40333979, 2025). "While we acknowledge that the pathogenesis of human BPD and emphysema is likely multifactorial, our study proposes a model in which HHIP deficiency disrupts stromal function, thereby impairing alveologenesis and contributing to the phenotypes of BPD and BPD-associated emphysema." (PMID 40333979, 2025). "Furthermore, reduced HHIP expression was observed in emphysema tissues, suggesting a protective role of HHIP in emphysema pathogenesis." (PMID 31323955, 2019). "Notably, HHIP has been implicated in both BPD and COPD/emphysema." (PMID 40333979, 2025). "We developed a therapeutic Fc-fused HHIP protein that mitigated BPD in neonatal mice and prevented adult emphysema." (PMID 40333979, 2025).
emphysema (continued). "In previous GWA studies, in mainly smokers, on classical COPD phenotypes like emphysema and chronic bronchitis, the well-known general COPD genes (HHIP, CHRNA and FAM13A) were consistently identified." (PMID 30845926, 2019).
colon cancer (6 papers, 2013 to 2024). "High HHIP expression was positively associated with DNA Methylation,and negatively associated with Metabolic Reprogramming In Colon Cancer,Notch Signaling Pathway,TNF Signaling,Glycolysis and Gluconeogenesis." (PMID 37568084, 2023). "Gene profiling of single cells revealed that RGS5-expressing myofibroblasts, CXCL14-expressing fibroblasts and HHIP+ myofibroblasts showed extensive upregulation of extracellular matrix genes, including collagen genes, in colon cancer tissues." (PMID 36463319, 2022). "The fibroblasts and myofibroblasts were visualized by anti-human RGS5, decorin, podoplanin/gp36, CD36, α-SMA, and HHIP antibodies in colon mucosa and colon cancer tissues." (PMID 36463319, 2022). "Together with the marked overall downregulation of GLI1 and HHIP, these results provide consistent evidence that stromal downstream Hh activity is diminished in colon cancer." (PMID 27492255, 2016). "Moreover, we noted that some of the mRNAs (ANLN, CFL2, FJX1, HHIP, PANX2, SCN3A, VSNL1 and ZIC2) were also associated with overall survival in patients with colon cancer." (PMID 29420609, 2018). "The proportion of HHIP+ myofibroblasts was not altered in colon cancer tissue compared to human colon mucosa." (PMID 36463319, 2022).
liver cancer (6 papers, 2019 to 2023). An epithelial or non-epithelial malignant neoplasm that arises from the liver. "Additionally, our bioinformatic analysis suggested that HHIP was downregulated in liver cancer and the downregulation of HHIP was associated with the PFS and RFS of HCC patients." (PMID 37039160, 2023). "Data from The Cancer Genome Atlas (TCGA) revealed that HHIP was considerably downregulated in a variety of cancers, including liver cancer." (PMID 37039160, 2023). "These analyses demonstrated that HHIP was a key TSG controlling liver cancer cell proliferation and cell viability; in fact, only modest changes in cell viability were achieved when individually targeting MT1M, PZP, and TTC36." (PMID 37120619, 2023). "HHIP is significantly downregulated in human liver cancer cells, increased HHIP expression can induce apoptosis to significantly inhibit the proliferation, migration and invasion of cancer cells in liver cancer." (PMID 37568084, 2023). "The expression of TCF21 and HHIP was negatively correlated with miR‐25‐3p expression in HBV‐positive patients with liver cancer." (PMID 32525231, 2020). "This shows that TCF21 and HHIP have synergistic effects on the viability, proliferation, apoptosis, invasion and migration of HepG2.2.15 cells and both TCF21 and HHIP play extremely important anti‐tumour roles in HBV‐positive liver cancer cells." (PMID 32525231, 2020). "The expression of HHIP was significantly positively correlated with TCF21 expression in HBV‐positive patients with liver cancer and CHB patients with PNALT (≥A2)." (PMID 32525231, 2020). "TCF21 and HHIP are two target genes of miR‐25‐3p that have anti‐tumour effects in HBV‐positive liver cancer." (PMID 32525231, 2020). "Many studies have shown that HHIP plays an anti-tumor role in GC, liver cancer and glioblastoma." (PMID 34532291, 2021). "Therefore, both TCF21 and HHIP, which were identified as target genes of miR‐25‐3p and were downregulated in liver cancer, were used to follow up studies." (PMID 32525231, 2020). "Therefore, HHIP also can be utilized as a potential therapeutic target for liver cancer." (PMID 37568084, 2023). "Exosomes secreted by CHB patients with PNALT and liver tissue inflammation grade ≥ A2 promoted the development of liver cancer by transferring miR‐25‐3p to inhibit the co‐expression of TCF21 and HHIP." (PMID 32525231, 2020). "Transfer of miR‐25‐3p by CHB‐PNALT‐Exo promoted the development of liver cancer by inhibiting the co‐expression of TCF21 and HHIP." (PMID 32525231, 2020). "The results showed that TCF21 directly interacted with HHIP and was positively correlated with HHIP in CHB patients with PNALT and HBV‐positive patients with liver cancer." (PMID 32525231, 2020). "HHIP expression levels were also medium in normal liver tissues; however, HHIP expression levels in liver cancer tissues were not reported in the Human Protein Atlas database." (PMID 32525231, 2020). "However, the related mechanisms and the role of HHIP in liver cancer have not been reported." (PMID 32525231, 2020).
asthma (5 papers, 2017 to 2022). "In a previous study, we have showed that HHIP, FAM13A1, AGER and RARB associated with pre-bronchodilator lung function in subjects with asthma." (PMID 30068317, 2018). "In a study by Li and colleagues, a subset of normal lung function genes associated with the hedgehog signaling pathway including the patched homolog 1 (PTCH1) and hedgehog interacting protein (HHIP) predicted lung function decline in white and African American subjects with asthma." (PMID 36230980, 2022). "All the evidence indicates rs1980057 in HHIP, rs2869967 in FAM13A1, and rs2070600 in AGER are functionally relevant SNPs important for lung function in the general population and in subjects with COPD or asthma." (PMID 30068317, 2018).
hepatocellular carcinoma (4 papers, 2020 to 2025). A malignant tumor that arises from hepatocytes. "CircFAM114A2 exerts a tumor suppressor role in hepatocellular carcinoma (HCC) through miR‐630/HHIP axis and may be served as a potential diagnostic and therapeutic biomarker for HCC patients." (PMID 37039160, 2023). "Studies have shown that HHIP is the target gene of miR-25-3p in hepatocellular carcinoma." (PMID 34532291, 2021). "Moreover, the Hedgehog-interacting protein (HHIP) is silenced by promoter hypermethylation in lung and hepatocellular cancers, and this was correlated with the downregulation of the protein." (PMID 33396427, 2020). "In hepatocellular carcinoma (HCC), silencing of tumor suppressor genes such as HHIP, MT1M, PZP, and TTC36 is a key driver of carcinogenesis." (PMID 41335282, 2025).
breast carcinoma (3 papers, 2020 to 2025). "Interestingly, we found that Gli1 was significantly up‐regulated in breast cancer tissues, whereas PTCH1, SMO, Gli1 and HHIP at mRNA and protein levels were all down‐regulated after controlling for EGOT overexpression." (PMID 32150666, 2020).
colorectal cancer (3 papers, 2019 to 2022). A primary or metastatic malignant neoplasm that affects the colon or rectum. "HHIP binds to all Hh ligands, and acts as a negative regulator of the Hh/GLI signaling pathway, which is abnormally activated in colorectal cancer, prostate cancer, and other cancers." (PMID 36482325, 2022).
glioblastoma (3 papers, 2021 to 2023). The most malignant astrocytic tumor (WHO grade IV). "Here we report for the first time the variable gene expression behavior of RUNX1T1 and HHIP related to tumor location within a glioblastoma context." (PMID 34157951, 2021). "Finally, we focused our attention on RUNX1T1 and HHIP gene, the genes more affected by the exosome-derived miRNAs in glioblastoma cell lines subjected to invasion." (PMID 34157951, 2021). "In T98G glioblastoma cell line we found a combination of 4 miRNAs (miR-30e-3p, miR-3605-5p, miR-4762-5p, miR-4768-5p) which are targeting the same gene, RUNX1T1, and a combination of 3 miRNAs (miR-4768-5p, miR-375, miR-5701) targeting the HHIP gene (darker green squares)." (PMID 34157951, 2021).
leukemia (3 papers, 2014 to 2022). A malignant (clonal) hematologic disorder, involving hematopoietic stem cells and characterized by the presence of primitive or atypical myeloid or lymphoid cells in the bone marrow and the blood. "Pretreatment with azacitidine induced demethylation of the HHIP gene, partially restored HHIP expression, and reduced the leukemia promoting effect of the primary AML stromal cells." (PMID 35990601, 2022). "As HHIP is likely to regulate stem cell-like characteristics of either leukemia cells, or stromal cells that support them it should be considered a high-value target." (PMID 24959420, 2014).
lung diseases (3 papers, 2015 to 2025). "Furthermore, allelic variations in Hedgehog‐interacting protein (HHIP), an endogenous inhibitor of Hedgehog signaling, are associated with smoking‐related lung diseases." (PMID 41383023, 2025).
Obesity (3 papers, 2022 to 2023). Accumulation of substantial excess body fat. "Further, in the current cohort, circulating HHIP levels were significantly associated with glucose and lipid metabolism disorders, obesity, IR and PCOS, and were significantly negatively correlated with serum adipoq levels and the M-value of EHC." (PMID 36769536, 2023). "Recently, it has been reported that HHIP mRNA expression in the islets of mice with obesity (ob/ob mice) was significantly increased, and that the serum HHIP concentrations were significantly increased in patients with IFG, IGT, and newly diagnosed T2DM." (PMID 36769536, 2023). "Recently, several human and animal studies have found that HHIP is associated with metabolic diseases such as T2DM and obesity." (PMID 36769536, 2023). "Circulating HHIP levels were significantly correlated with adiponectin (Adipoq) levels, obesity, IR, and metabolic indicators." (PMID 36769536, 2023). "At this point, it should be noted that molecules of the Hh signaling pathway can be considered biomarkers for obesity, such as the Hedgehog-interacting protein (HHIP1), which is significantly reduced in the serum of obese patients." (PMID 35626717, 2022). "In addition, the levels of circulating HHIP were significantly related to obesity, IR indicators, and glucose and lipid metabolism." (PMID 36769536, 2023). "In addition, an analysis on a diabetes-related genome-wide database found that HHIP mRNA expression in the islets of mice with obesity (ob/ob mice) was significantly increased compared with lean mice." (PMID 36769536, 2023). "Studies have found that HHIP (hedgehog interacting protein), MUC5AC, CYP2A6, and PCK1 can promote obesity." (PMID 38137330, 2023).
diabetes (2 papers, 2023). "Serum human hedgehog-interacting protein (HHIP) concentration is associated with diabetes." (PMID 36769536, 2023). "Therefore, serum HHIP concentration is considered to be associated with diabetes and metabolic abnormalities." (PMID 36769536, 2023). "CYP1A1, HHIP (hedgehog interacting protein), AGTR2, CYP2A6, and PCK1 are involved in growth and development of diabetes mellitus." (PMID 38137330, 2023). "Further, recently, a study found that the serum HHIP concentration increased significantly in patients with impaired fasting glucose (IFG), impaired glucose tolerance (IGT) and newly diagnosed type 2 diabetes mellitus (T2DM)." (PMID 36769536, 2023).
hepatoblastoma (2 papers, 2021 to 2024). Hepatoblastoma (HB) is a malignant hepatic tumor and is the most common pediatric liver cancer. "The UHRF1/HAUSP/DNMT1 complex was also detected on the promoters of HHIP and IGFBP3, two key TSGs in hepatoblastoma, and this interaction caused the inhibition of these genes." (PMID 33922029, 2021). "Interestingly, the depletion of UHRF1, but not of its partner HAUSP, significantly increased the expression of the HHIP and IGFBP3 genes and decreased the H3K9me2 mark at the HHIP and IGFBP3 TSG loci, leading to the inhibition of hepatoblastoma cell growth." (PMID 33922029, 2021). "Employing chromatin immunoprecipitations (CHIP), one study has suggested that E3 ubiquitin-like containing PHD and RING finger domain 1 (UHRF1) may play a crucial role in the profound silencing of tumor suppressor genes (TSGs) such as HHIP, IGFBP3, and SFRP1 in hepatoblastoma." (PMID 38390281, 2024).
mesothelioma (2 papers, 2022 to 2025). A usually malignant and aggressive neoplasm of the mesothelium which is often associated with exposure to asbestos. "Suppressing Hedgehog signalling reduced cell viability in MPM cells, and treatment with vismodegib in a rat model of mesothelioma reduced the expression of target genes such as GLI1, HHIP and PTCH1." (PMID 36138075, 2022).
adenomyosis (1 paper, 2025). The growth of endometrial tissue inside the muscular wall of the uterine corpus. "IHH, as well as its transcription factor, receptor, and target gene (SOX17, PTCH1, and HHIP, respectively), exhibiting spatial expression characteristics, were highly expressed in the invaginating site of adenomyosis." (PMID 40190183, 2025).
Airway obstruction (1 paper, 2021). Obstruction of conducting airways of the lung. "Future evaluations on the stress-induced airway obstruction such as under methacholine challenge in Hhip+/- mice may facilitate a better understanding of the regulation of HHIP on airway function." (PMID 33907231, 2021).
basal cell carcinoma (1 paper, 2010). A carcinoma involving the basal cells. "HHIP antagonizes all three of the hedgehog family of ligands (SHH, DHH and IHH) and has been shown to be down-regulated in numerous epithelial tumor types with the notable exception of basal cell carcinoma where it is upregulated." (PMID 20860831, 2010).
colorectal tumors (1 paper, 2009). "Furthermore, we also found that DNA methylation of SMO and HHIP were closely linked to colorectal tumors with BRAFV600E." (PMID 20027224, 2009).